ICAM1 (intercellular adhesion molecule 1)
Diseases named in the same sentence as ICAM1 in open-access papers (continued):
Sharing a sentence is not in itself a finding about the gene and the disease.
tumor (continued). "Despite this, some investigations have indicated non-engineering approaches, such as IFN-γ treatment, that, while increasing PD-L1 expression by solid tumors, would also pave the way for bypassing PD-L1/PD-1 by enhancing ICAM-1 expression on tumor cells." (PMID 37020537, 2023). "Our study demonstrated another possibility that overexpression of CXCL10 and ICAM-1 in tumor cells plays a significant role to help CD8+ T cell adhesion and further activation by recognizing the alloantigens in A549 cells." (PMID 36688994, 2023). "In this study, we repeatedly confirmed that tumor-selective overexpression of ICAM1 at protein and mRNA levels in well-recognized CCA cell lines and clinically-relevant tumor tissues." (PMID 37717087, 2023). "The core part focuses on the potential of exosomes as important messengers to carry unique cargo proteins, such as PD-L1, MHC, and ICAM-1, in the remodeling and treatment of the tumor immune microenvironment." (PMID 37670933, 2023). "The following two mechanisms were proposed to explain this; 1) miR-1246 is taken up by ECs in high metastatic tumor EVs, thus inducing ICAM-1 expression via STAT3 activation in ECs." (PMID 37124539, 2023). "The results led us to propose a cancer immune evasion mode wherein mutant tumor cells proactively downregulate ICAM1 expression and escape the adhesion and interaction with T cells in the TME." (PMID 36871040, 2023). "ICAM-1 expressed on ECs is the key molecule for tumor cells to adhere to ECs and is induced via STAT3 activation." (PMID 37124539, 2023). "Third, our transcriptomic profiling results provide new biological insights that ICAM1-DXd affects CCA tumor immune microenvironment mainly through upregulating type I interferon signaling pathway." (PMID 37717087, 2023). "Based on this discovered CCA therapeutic target, two ICAM1 ADCs were designed and constructed with different chemical linkers and payloads, and then their anti-tumor efficacies were evaluated on CCA by in vitro and in vivo experiments." (PMID 37717087, 2023). "ICAM-1 expression correlated with younger age at diagnosis (p = 0.0312) and smaller tumor size (p = 0.0443)." (PMID 36906717, 2023). "By promoting interactions between tumor cells and endothelial cells, ICAM1 facilitates the adhesion and transmigration of cancer cells to distant organs." (PMID 37671167, 2023). "Activation of endothelial cells can lead to their expression of adhesion molecules including E-selectin, P-selectin, vascular cell adhesion molecule (VCAM)-1 and intercellular adhesion molecule (ICAM)-1, all of which can facilitate tumor cell binding." (PMID 37770941, 2023). "EGF influences ICAM-1 expression by inducing VEGF-C production, which promotes VEGF receptor 2 (VEGFR3) signaling in tumor cells and induces integrin/ICAM-1, which ultimately leads to tumor growth and migration." (PMID 37298230, 2023). "The anti-tumor activity of ICAM1-DXd and ICAM1-MMAE on tumor growth at the end of treatment were 73% and 62%, respectively, in comparison with the PBS control group." (PMID 37717087, 2023). "This study proves that the CX3CL1‐CX3CR1 axis is vital in promoting ICAM‐1‐regulated tumour metastasis." (PMID 37082943, 2023). "The results revealed that ICAM1 on tumor cells orchestrates the antitumor immune response, especially in adaptive immunity." (PMID 37612741, 2023). "Upregulation of ICAM1 expression in human cancers should result in release of sICAM-1, favoring tumor growth." (PMID 37732732, 2023). "In the inflamed state, endothelial ICAM-1 and neutrophil CD11b were upregulated to better support neutrophil and tumor cell aggregation." (PMID 37064144, 2023). "Overall, both ICAM1 ADCs showed significant tumor growth inhibition in both in vivo treatment models, and ICAM1-DXd is consistently more effective than ICAM1-MMAE in both CCA tumor models." (PMID 37717087, 2023).
tumor (continued). "The anti-tumor activity of two ADCs was also determined by weighing the tumor mass at the end point, and the inhibitory efficiency of tumor weight by ICAM1-DXd and ICAM1-MMAE were 59% and 53% of PBS, respectively." (PMID 37717087, 2023). "Ectopic expression of Icam1 in Lkb1-deficient tumor increases homing and activation of adoptively transferred SIINFEKL-specific CD8+ T cells, reactivates tumor-effector cell interactions and re-sensitises tumors to ICB." (PMID 36871040, 2023). "ICAM1 expression on tumor cells or surrounding stromal cells can modulate immune cell interactions and affect the infiltration of cytotoxic T cells into the tumor." (PMID 37671167, 2023). "VCAM‐1 and ICAM‐1 play critical roles in cell adhesion to the endothelium and tumour development, cell proliferation, invasion and angiogenesis." (PMID 37082943, 2023). "ICAM-1 enhances the adhesion of leukocytes, inflammatory cells, and tumor cells to endothelial cells by specifically binding to its receptor." (PMID 38065859, 2023). "Various degrees of inflammation are typically correlated with tumor development, and the expression of ICAM-1 in the lymphatic vessels is upregulated during inflammation." (PMID 37274228, 2023). "Enhanced ICAM-1 expression on target tumor cells led to an increase in conjugation formation with PD-1high hHER2-CAR-T cells followed by greater lytic granule exocytosis (measured as CD107a expression), compared to PD-1low CAR-T cells." (PMID 37388744, 2023). "Interferon (IFN)-γ upregulates ICAM-1 expression on tumor cells and ICAM-1 on TDEs mediates T cell inhibition principally by interacting with activated LFA-1 on CD8+ T cells." (PMID 37007125, 2023). "We further explored the biological activities of ICAM1 ADCs on the tumor microenvironment of a patient-derived xenograft (PDX) of CCA via transcriptomic profiling, providing biomechanistic insights of ICAM1 ADC treatment." (PMID 37717087, 2023). "IL-17A stimulation reduced LFA-1 surface expression on stem-like exhausted CTLs and the counterpart ICAM-1 (intracellular adhesion molecule-1) on tumor vascular endothelium." (PMID 37605139, 2023). "The high-ICAM1 group surpassed in terms of stromal cells (p=0.037), tumor cell purity (p=3.8e-10), and immune score (p=5.4e-08)." (PMID 37671167, 2023). "Meanwhile, RT can enhance the anti-tumor effect of the immune system by up-regulating immunogenic cell surface markers such as intercellular cell adhesion molecule 1 (ICAM-1), major histocompatibility complex class 1 (MHC-1) and Fas." (PMID 38023216, 2023). "Secondly, through two in vivo models, ICAM1-DXd and ICAM1-MMAE showed potent anti-tumor activities in comparison with the first-line chemodrug Gemcitabine." (PMID 37717087, 2023). "This PDX model features a low ICAM1 expression, which is about 500-fold lower than that of HuCCT1 tumor xenograft." (PMID 37717087, 2023). "CX3CL1, as a prognosis indicator, promoted tumour cell migration, invasion and ICAM‐1 expression by activating CX3CR1/PLCβ/PKCα/c‐Src/c‐Jun/AP‐1 pathway." (PMID 37082943, 2023). "Altogether these results show that in our system, ICAM-1 plays a crucial role in the productive interaction between tumor and activated CTL and that ICAM-1 depletion has more effect than PD-1 overexpression in inducing killing resistance." (PMID 37732732, 2023). "This schematic illustrates the process of cell releasing exosomes (left) and the mechanism and importance of PD-L1, MHC, and ICAM-1 on the surface of exosomes in tumor immune escape (right)." (PMID 37670933, 2023). "On the other hand, LFA-1/ICAM-1 interaction has potential anti-tumor effect because it is an alternative costimulatory signaling to activate anti-tumor cytotoxic T cells." (PMID 36895477, 2023). "In a third study, using ICAM-1 Fabs, tumor MFI decreased to such an extent compared to the full-sized antibody that it matched that of non-specific controls." (PMID 34642899, 2023).
tumor (continued). "Greater expression of ICAM-1 molecules in tumor tissue can also result in enhanced tumor cell apoptosis." (PMID 37569878, 2023). "Tumor cells present an overexpression of ICAM-1, which provides selectivity to the virus for damaged cells, avoiding the infection of healthy cells." (PMID 37771727, 2023). "Recently, by comparing primary tumor cells with cells metastasized into the lungs using single-cell RNA sequencing, we identified that ICAM-1 in TNBC cells is a new driver for TNBC metastasis." (PMID 37345070, 2023). "Accordingly, we systemically evaluated the effects of treatment with palbociclib or the combination therapy on the tumor microenvironment in the setting of ICAM1 depletion." (PMID 36871040, 2023). "Recently, we found that ICAM-1 expression was increased by 200-fold in lung metastases, compared to primary tumor cells in several TNBC PDX models." (PMID 37345070, 2023). "In comparison, Gemcitabine showed almost no inhibitory effect on CCA tumors, while ICAM1 antibodies showed a certain inhibitory effect on tumor growth, but was significantly less effective than ICAM1-MMAE and ICAM1-DXd treatments." (PMID 37717087, 2023). "Our transcriptomic RNA-seq analysis further indicated that ICAM1-DXd also activates anti-tumor immunity in PDX models." (PMID 37717087, 2023). "Although involved in tumor invasion and metastasis, the mechanism of action of intercellular adhesion molecule 1 (ICAM1), a trans-membrane glycoprotein, in TNBC is ambiguous." (PMID 37671167, 2023). "The expression of full-length ICAM1 rescued antigen-specific tumor cell killing by CTLs in ICAM1 KO cells confirming the important role of ICAM-1 in controlling CTL-mediated killing." (PMID 37732732, 2023). "We previously demonstrated that Pom increases immune surface markers B7-2 and ICAM-1 in certain EBV infected tumor cell lines and that this leads to increased T-cell activation and NK-mediated cell killing in Daudi cells." (PMID 37463943, 2023). "Blocking EGFR or ICAM-1 in TAM by drugs or antibodies inhibits tumor tissue formation and disease progression in mouse models of ovarian." (PMID 37005667, 2023). "Intercellular adhesion molecule 1 (ICAM1), a member of the immunoglobulin superfamily, has been shown to promote tumor cell adhesion to endothelial cells and facilitate metastasis." (PMID 38023192, 2023). "In order to investigate the role of ICAM-1 isoforms and such mutants important for ICAM-1 shedding, we transfected ICAM1 KO or WT cells with plasmids encoding for ICAM-1 variants and investigated tumor cell killing by CTLs." (PMID 37732732, 2023). "Tumor-derived GDF-15 thus inhibits the LFA-1:ICAM-1 axis in human T cells, thereby interfering with T cell post rolling arrest, firm adhesion to endothelia, crawling and diapedesis across activated blood vessels." (PMID 37474523, 2023). "Hif1a transcript levels were significantly higher in T-ALL cells in both organs, implicating hypoxia as a potential mechanism underlying elevated ICAM-1 and VCAM-1 levels in tumor-associated myeloid cells." (PMID 37805579, 2023). "ICAM-1 promotes the adherence of T-cells to tumor cells and has been found to provide an alternative costimulatory signal that restores the cytotoxic function of CTLs, and FAS activates the caspase apoptosis pathway." (PMID 37754534, 2023). "ICAM1 plays an important role in promoting the adhesion of inflammatory sites, controlling tumor deterioration and metastasis, and regulating the body’s immune response." (PMID 37592228, 2023). "Western blot analysis revealed that both ANL and AS treatments elicited higher levels of vascular cell adhesion molecule-1 (VCAM-1) and intracellular adhesion molecule-1 (ICAM-1) in tumor tissue, especially on the surface of CD31+ tumor vascular cells." (PMID 37620331, 2023). "MUC-1 expression on tumor cells promotes metastasis by binding to intercellular adhesion molecule-1 (ICAM-1) in endothelial cells." (PMID 36895477, 2023).
tumor (continued). "To elucidate its underlying biomechanism, we performed a transcriptomic RNA sequencing (RNA-seq) to profile the signaling pathways and key genes affected by ICAM1-DXd treatment in PDX tumor tissues." (PMID 37717087, 2023). "ICAM-1 is present on tumor cell-derived exosomes as well, which can bind to leukocytes, thus preventing them from adhering to activated endothelial cells." (PMID 37007125, 2023). "‐Blockage of spheroid formation by clodronate‐liposome‐mediated macrophage depletion or anti‐ICAM‐1 antibodies delayed tumor growth.‐Pharmacological blockade of EGFR delayed tumor growth." (PMID 36658699, 2023). "Together, our findings suggest that ICAM-1-suPAR-CD11b axis promotes TNBC metastasis via enhancing tumor cell and neutrophil binding, which provides a strong rationale for targeting this axis to block TNBC metastasis." (PMID 37345070, 2023). "In an animal model, inhibiting VEGF/VEGFR signaling or neutralizing ICAM-1 slowed spheroid and tumor growth." (PMID 37298230, 2023). "ICAM1 expression corresponded well with the stromal cell quantity (R-0.26, p=0.0035), tumor purity (R=0.52, p=3.2e-10), and immune score (R=0.59, p=2.2e-13)." (PMID 37671167, 2023). "Higher expressions of the genes involved in the Tumor Microenvironment Pathway, including ICAM1, SLC2A1, and TNC were found in the PMCs of the LCP group." (PMID 37649596, 2023). "In Icam1-/- mice, spleen and liver weights were reduced to levels comparable to tumor-free littermate Icam1+/- controls." (PMID 37805579, 2023). "Based on recent findings discussed here showing a strengthening of the adhesion, we assumed that the synapse formed between CAR T cells and tumor cells will evolve over time and get structured due to ICAM-1 upregulation and interaction with LFA-1." (PMID 36189315, 2022). "It has been reported that NSUN2 methylates ICAM-1 (Intercellular Adhesion Molecule 1) mRNA and promotes its translation, thus inhibiting M2-macrophage polarization and suppressing tumor metastasis." (PMID 35365216, 2022). "ICAM-1 is an adhesion protein expressed on the surface of endothelial cells, monocytes, lymphocytes and tumor cells." (PMID 36386163, 2022). "Multiplex cytokine assays revealed that macrophage-tumor coculture increased macrophage secretion of IL-1β, thereby inducing the expression of intercellular adhesion molecule 1 (ICAM1; also known as CD54) in HNSCC." (PMID 36264639, 2022). "Tumor growth can be facilitated by the expression of adhesion molecules (e.g., ICAM-1), considered a signal molecule." (PMID 35745643, 2022). "Further research is needed to clarify the role of SOD3 on ICAM-1 transcription in the tumor endothelium." (PMID 35267534, 2022). "ICAM1 promoted tumor stemness and increased the resistance of HNSCC to chemotherapy, particularly DTX." (PMID 36264639, 2022). "The dramatic upregulation of ICAM1 implies a potential role in mediating the interaction between macrophages and tumor cells responsible for chemoresistance in HNSCC." (PMID 36264639, 2022). "More surprising was the ability of CAR T cells to progressively strengthen their interaction with tumor cells that initially expressed low levels of ICAM-1 and to do so in an IFNγ-dependent manner." (PMID 36189315, 2022). "RT can also alter the tumor microenvironment and tumor-associated macrophages, induce vascular endothelial cells to express adhesion molecules (e.g., VCAM-1, E-selectin, and ICAM-1), and increase vascular permeability and chemokine expression." (PMID 36140312, 2022). "- TNF-α: TNF-α increases the expression of intracellular adhesion molecule−1 (ICAM-1), a receptor required for leukocyte adhesion and tumor invasion." (PMID 35252243, 2022). "LFA1 is expressed on lymphocytes and it is a crucial for T cell entry into mammalian lymph nodes and tissues while ICAM1 on tumor target cells or endothelial cells." (PMID 35281003, 2022).
tumor (continued). "Productive interactions between LFA-1 and ICAM-1 can result in cytotoxic T lymphocytes (CTLs) exiting the systemic circulation, infiltrating the tumor tissue, and triggering effector functions, resulting in tumor destruction." (PMID 35552271, 2022). "T cells are important for killing tumor cells and the increased ICAM-1 expression on CD8+ T cells activates the antitumor function of CD8+ T cells." (PMID 36505809, 2022). "The increased ICAM-1 expression on other cells in the TME also enhances the tumor infiltration and function of CTLs." (PMID 36505809, 2022). "In light of angiogenesis, MDSC-released VEGF was sufficient to prohibit the expression levels of various key adhesion molecules including ICAM-1 and VCAM-1 in tumor-associated ECs, thereby preventing the adhesion and extravasation of T cells." (PMID 36439137, 2022). "BZM treatment significantly reduced not only Sele, but also Icam1 and Vcam1, expression in the lungs of s.c. xenograft tumor-bearing mice and of E-selectin, ICAM-1, and VCAM-1 protein levels on ECs in vitro." (PMID 35031433, 2022). "Previously, such approaches were successfully used to identify tumor-specific antibodies like the anti-human C-type lectin-like molecule-1 antibodies for AML or anti-human ICAM-1 antibodies for MM therapy." (PMID 35784366, 2022). "More importantly, ICAM-1 contributes to the transendothelial tumor cell migration process and, thus, it has an active role in the metastatic potential of the tumor." (PMID 35740491, 2022). "ICAM‐1–induced tumor COX‐2 impaired the antitumor activity via binding LFA-1 during hepatic metastasis." (PMID 36016615, 2022). "This inflammatory cytokine, in line with prior studies upregulates ICAM-1 on tumor cells facilitating the formation of productive conjugates between CAR T cells and their targets." (PMID 36189315, 2022). "VEGF has been reported to exert immunosuppressive activity through the following mechanisms: Inhibition of DC maturation, accumulation of MDSCs in tumor, and decreases of ICAM-1 and VCAM-1 in vascular endothelial cells." (PMID 34958105, 2022). "Although we did not detect ROS or EMT marker levels in this study, the increased levels of prometastatic molecules pro-MMP-2 and ICAM-1 indicate that PM2.5 induces tumor metastatic activity." (PMID 36185331, 2022). "The tumor-targeting ability was further improved by the LFA-1/ICAM-1 interaction-dependent tumor vascular targeting and crossing effects." (PMID 35057015, 2022). "Higher serum ICAM-1 concentration has been shown in various cancers and mediated hematogenous metastasis, lymphatic metastasis and immune escape of tumor cells." (PMID 36386163, 2022). "Coxsackievirus A21 (CVA21), a novel intercellular adhesion molecule-1 (ICAM-1) virus, was applied for tumor-targeted immunotherapy." (PMID 35804953, 2022). "We have found that CAR T-cell initial activation was strongly dependent on the expression level of ICAM-1 on tumor cells." (PMID 36189315, 2022). "For various tumor cell lines, ICAM1 plays an important role in cell aggregation under suspension cultures; however, to the best of our knowledge, there are no reports about the roles of ICAM1 in hPSC adhesion." (PMID 35619172, 2022). "Vascular system dysregulation and inadequate endothelial energy in tumor tissues downregulate the expression level of intercellular adhesion molecule 1(ICAM1) and adhesion molecules VCAM1, which limits T cell infiltration in tumor tissues." (PMID 35935930, 2022). "ICAM-1 can increase the effect of NK cells on tumor cells, while its downregulation is a key mechanism by which cancer cells evade NK cell attack." (PMID 36238299, 2022).